HMGB1 (high mobility group box 1)
Diseases named in the same sentence as HMGB1 in open-access papers (continued):
Sharing a sentence is not in itself a finding about the gene and the disease.
glioma (continued). "In gliomas, GPR65 serves as the primary lactate receptor on TAMs, where it activates the cAMP/PKA/CREB pathway, induces high mobility group box 1 (HMGB1) secretion, and fosters glioma progression." (PMID 41152975, 2025). "In gliomas, HMGB1 has been shown to promote M1-like polarization of macrophages activate the NF-κB pathway by binding to RAGE, and enhance the release of the NLRP3 inflammasome." (PMID 40688353, 2025). "Grade IV glioblastoma, the most aggressive form of glioma, exhibits unique widespread tissue hypoxia characteristics, which can increase HMGB1 expression and extracellular release." (PMID 38529373, 2024). "Its upregulation inhibits glioma cell proliferation, migration, and invasion by downregulating HMGB1." (PMID 39759512, 2024). "The production of IL- 1β from glioma cells is responsible for the activation of TLR-4 and overexpression of HMGB1, which most likely gives rise to HLA-G, contributing to glioma immune evasion response." (PMID 38698968, 2024). "GPR65, highly expressed on TAMs, sensed lactate-stimulation in the TME, fueling glioma cells malignant progression through the secretion of HMGB1." (PMID 38576043, 2024). "In a mouse model of glioma, IGV001 stimulates the immune system by inducing the release of immunogenic cell death (ICD)-associated molecules such as ATP and HMGB1." (PMID 38420122, 2024). "Disrupting this feedback loop by GPR65-knockdown or HMGB1 inhibition mitigated glioma progression in vivo." (PMID 38576043, 2024). "Based on these findings, HMGB1 emerged as a potential candidate for validating the pro-tumor effects of lactate-GPR65 signals on TAMs in glioma." (PMID 38576043, 2024). "High levels of CXCL8 can stimulate tumor angiogenesis or recruit immunosuppressive cells, while tumor-infiltrating neutrophils contribute to the progression of gliomas by regulating the HMGB1/RAGE/CXCL8 axis." (PMID 39488622, 2024). "In summary, our findings highlight the dynamic crosstalk between TAMs and tumor cells mediated by lactate and HMGB1, which plays a pivotal role in promoting glioma progression." (PMID 38576043, 2024). "Blocking this feedback loop by targeting GPR65 or HMGB1 represents an attractive therapeutic option for glioma." (PMID 38576043, 2024). "In mouse glioma models, high-mobility group box 1 (HMGB1), an alarmin produced by dying cancer cells, activates TLR2 in dendritic cells (DCs) and leads to brain tumor regression." (PMID 39594997, 2024). "In glioma, it has been reported that HMGB1 can be passively released from dead cells into the extracellular space." (PMID 38529373, 2024). "GPR65, selectively highly expressed on TAMs in glioma, sensed lactate stimulation and fostered HMGB1 secretion via the cAMP/PKA/CREB signaling pathway." (PMID 38576043, 2024). "Inhibiting GPR65 or targeting HMGB1 showed anti-tumor potential for glioma in models, indicating as attractive targets for glioma." (PMID 38576043, 2024). "In our study, we elucidated the intricate interplay between TAMs and tumor cells mediated by lactate and HMGB1, which significantly promotes tumor progression in glioma." (PMID 38576043, 2024). "Collectively, our data suggest circ_0008285 contributes to the malignant phenotype of glioma cells by modulating the miR-384/HMGB1 pathway." (PMID 37575469, 2023). "In this study, increased cell-surface CRT expression and release of HMGB1 from the cell nucleus into the extracellular space indicated that 131I-hu4G4 therapy against gliomas elicited glioma cell ICD, which enhanced the tumor immunogenicity." (PMID 37705739, 2023). "In the case of pz I-PDT, glioma cell death was accompanied by a gradual increase in the release of two crucial DAMPs, ATP and HMGB1, during the 24 h after light irradiation." (PMID 37896190, 2023). "After pz I-PDT, glioma cell death was accompanied by a gradual increase in ATP and HMGB1 release during the 24 h after light irradiation." (PMID 37896190, 2023).
glioma (continued). "Meanwhile, the regulatory relationship of circ_0008285, miR-384, and high mobility group protein B1 (HMGB1) was explored in glioma cells, and we explored the effects of circ_0008285/miR-384/HMGB1 pathway on glioma cells." (PMID 37575469, 2023). "Endogenetic noncoding RNA, such as miR-339-5p, inhibit angiogenic mimicry, migration, and invasion of glioma cells by inhibiting the PTP4A1/HMGB1 signaling pathway." (PMID 37759870, 2023). "Taking into account the high immunogenic potential of pz I-PDT and pz III-PDT, we analyzed the levels of several DAMPs, such as ATP and HMGB1, released from glioma GL621 cells at different time points after pz-based PDT." (PMID 37896190, 2023). "HMGB1 is highly expressed in COAD tissues, and the overexpression of HMGB1 in glioblastoma is thought to promote self-renewal of glioma stem cells." (PMID 37600653, 2023). "Functional experiments demonstrated that circ_0008285 promoted the malignant phenotype of glioma cells by miR-384/HMGB1 axis." (PMID 37575469, 2023). "The binding of RAGE receptors in glioma-associated microglia to various ligands like advanced glycation endproducts (AGEs), S100 proteins and high mobility group box 1 (HMGB1) mediates tumor angiogenesis and promotes glioma invasion and progression." (PMID 37700840, 2023). "Functional experiments suggested that circ_0008285 contributes to glioma cell proliferation and survival by modulating miR-384/HMGB1 pathway and supporting the malignant phenotype of glioma cells." (PMID 37575469, 2023). "It has been reported that neutrophil extracellular traps (NETs) produced by tumor-infiltrating neutrophils (TINs) mediate the interaction of glioma and TAMs by regulating the HMGB1/RAGE/IL-8 axis." (PMID 37759870, 2023). "Overexpression of miR-665 in glioma cells inhibits tumor cell proliferation, migration, and invasion by targeting high mobility group box 1 (HMGB1) and High Mobility Group AT-hook 1 protein (HMGA1), deactivating the Wnt/β-catenin pathway." (PMID 37894282, 2023). "Our results suggested that circ_0008285 overexpression sustains glioma cell proliferation and survival by acting as a sponge for miR-384 and maintaining the HMGB1 level." (PMID 37575469, 2023). "One study revealed that HMGB1 interaction with RAGE/NFκB receptors from glioma cells induces IL-8 expression in tumor cells." (PMID 37292196, 2023). "Recently, studies on the role of HMGB1 in gliomas, especially glioblastomas, have been published in several journals." (PMID 37759870, 2023). "In order to test if HMGB1 also directly modulated EC function, we tested the ability of CMs derived from infected glioma cells ± HMGB1 neutralizing antibody to activate ECs." (PMID 36789106, 2023). "The HMGB1 levels in the culture supernatants of the PDT-treated glioma GL261 cells were measured with a sensitive ELISA." (PMID 37896190, 2023). "In glioma cells, NETs are thought to induce the IL-8 expression, which is correlated with tumor burden and prognosis through a HMGB1- and RAGE/ERK/NF-kB axis-dependent manner." (PMID 35711434, 2022). "In glioma, high-mobility group box 1 (HMGB1) derived from NETs binds to receptor for advanced glycation end products (RAGE) expressed in glioma tissue, activating the NF-κB signalling pathway to promote IL-8 secretion, which promotes neutrophil infiltration." (PMID 35860278, 2022). "Based on this, the present research investigated the expressing level of miR-339-5p in glioma and its molecular mechanism in glioma and its role in the PTP4A1/HMGB1 pathway, providing a valuable reference for the diagnoses and therapies of glioma." (PMID 35872698, 2022). "In parallel, the Newcastle disease virus (NDV) Hitchner B1 strain induced surface translocation of CRT and HMGB1 secretion in glioma cells, which produced a long-term, tumor-specific immunological memory response in an orthotopic glioma model." (PMID 36755812, 2022).
glioma (continued). "Blockade of HMGB1-RAGE interaction by soluble or mutated RAGE resulted in suppression of tumor growth and metastasis in glioma." (PMID 35610613, 2022). "Ferroptosis, an iron-mediated and lipid peroxidation-driven necrotic cell death, can induce the secretion of ATP and the release of HMGB1 in fibrosarcoma and glioma." (PMID 35046546, 2022). "To determine the expression pattern of the TIM3 ligands, galectin 9, PtdSer, CEACAM1, and HMGB1 in gliomas, we examined the RNA-sequencing data of gliomas from GlioVis data portal for the visualization and analysis of brain tumor expression datasets." (PMID 33800561, 2021). "Due to its implications in neuro-inflammation, HMGB1 has been considered as a therapeutic target in gliomas." (PMID 34975408, 2021). "Our study demonstrated for the pivotal role of HMGB1 in promoting GSCs formation in patient-derived primary glioma cells upon TMZ treatment." (PMID 33614649, 2021). "Lipid peroxidation and ferroptosis induced by photodynamic therapy induced dying glioma cells to release DAMPs such as calreticulin, high mobility group protein B1 (HMGB1) and ATP that can be swallowed by DCs, stimulating DC maturation and activation." (PMID 34211978, 2021). "Serum HMGB1 level is quite low in glioma patients untreated or treated with TMZ, in contrast with HMGB1 in culture in our experiments." (PMID 33614649, 2021). "As a DNA-binding protein, HMGB1 is well-conserved, and many studies have shown that it accelerates the development of gliomas." (PMID 34354995, 2021). "Examined by EdU incorporation assay, down-regulation of HMGB1 significantly inhibited the viability of U251 glioma cells, and also abolished the promotion effect of YAP." (PMID 33726796, 2021). "To gain insight into the clinical significance of YAP and HMGB1 in glioma samples, we firstly analyzed TCGA and CGGA database." (PMID 33726796, 2021). "Our study showed that TMZ treatment promoted GSCs formation by glioma cells; TMZ treatment of biopsy-derived glioblastoma multiforme cells upregulated HMGB1; HMGB1 altered gene expression profile of glioma cells with respect to mRNA, lncRNA and miRNA." (PMID 33614649, 2021). "In our cohort of glioma patients, we found that the serum levels of HMGB1 negatively correlated with the percentage of TREM-1+ Mo and with the TREM-1/TREM-2 ratio." (PMID 32684831, 2020). "Kaplan-Meier tests revealed that high HMGB1 levels correlate with poor glioma prognosis, and correlation analysis showed that HMGB1 levels inversely correlate with miR-107 expression in glioma tissues." (PMID 32913464, 2020). "The result showed that while CpG-ODN did not significantly upregulate stemness-related transcription factors in primary glioma cells, HMGB1 did show this effect." (PMID 32843056, 2020). "We further demonstrated that IL-8 was highly expressed in patients with high-grade glioma, and that NETs induced IL-8 expression in glioma cells in a HMGB1- and RAGE/ERK/NF-κB axis-dependent manner." (PMID 32296583, 2020). "Similar studies have also demonstrated the difference between the protein patterns of normal and glioma cells and the opposite effect of extracellular high-mobility group protein 1 (HMGB1) and astrocytic HMGB1 on SASH1 gene expression in one glioma cell line." (PMID 33178687, 2020). "The present study has shown that the upregulation of HMGB1 in glioma tissues is correlated to poor prognosis." (PMID 32913464, 2020). "Lastly, HMGB1, a damage associated molecular pattern (DAMP) that triggers TLR signaling, also upregulated stemness markers in glioma cells." (PMID 32843056, 2020). "Very interesting was the finding of a positive correlation of the level of HMGB1 in glioma patients with percentage of CD14+ TREM-2+ Mo (P = 0.007)." (PMID 32684831, 2020). "The RT-qPCR analysis revealed that miR-107 mimics decreased the expression of HMGB1 in glioma cells." (PMID 32913464, 2020).
glioma (continued). "We also verified in the present study that HMGB1, a protein present in large amounts in glioma cell nuclei, contributed to SASH1 gene methylation, thereby resulting in downregulated SASH1 expression." (PMID 31138780, 2019). "The cancer atlas of HMGB1 protein showed that the expressionlevel was highest in carcinoid, glioma, head and neck cancer,while lowest in testis cancer detected with CAB-antibody(CAB005873) in silico." (PMID 31485132, 2019). "TP73-AS1 participates in cancer biology through the interactions with multiple downstream cancer-related pathways, such as HMGB1/RAGE pathway in both glioma and liver cancer." (PMID 31015368, 2019). "Our study highlights the role of EV MALAT1-miR-129-5p-HMGB1 in the modulation of the inflammatory response in microglial cells, which holds great promise to serve as a therapeutic target for glioma treatments." (PMID 32117213, 2019). "HMGB1, a highly conserved nucleoprotein, has been reported to play a role in gliomagenesis and glioma progression." (PMID 31138780, 2019). "Further investigation revealed that TP73-AS1 competed with HMGB1 for miR-142 binding to modulate HMGB1 expression via an miR-142 sponge, which participated in the modulation of glioma cell proliferation and invasion." (PMID 31652459, 2019). "Silencing of TP73-AS1 inhibited glioma cell proliferation, invasion and high mobility group box 1 protein (HMGB1) protein expression." (PMID 31652459, 2019). "In this study, we verified that HMGB1 expression is increased in C6 glioma cells compared with rat primary astrocytes." (PMID 31138780, 2019). "Increasing levels of HMGB1 expression significantly correlated with reduced survival times when all patients with glioma were considered (P=0.045)." (PMID 25574225, 2015). "To elucidate the molecular mechanism by which miR-129-2 exerts its inhibitory effect on glioma cells, we predicted potential targets of miR-129-2 and focused on HMGB1 considering the involvement of HMGB1 in the pathogenesis of many human cancers." (PMID 25772485, 2015). "The positive rates of HMGB1 expression in low-grade gliomas (LGGs, grades I and II) and high-grade gliomas (HGGs, grades III and IV) were 63.0% (17/27) and 86.8% (33/38), respectively, and the positive rates in HGG were higher than those in LGG (P=0.024)." (PMID 25574225, 2015). "In this study, we inhibited HMGB1 expression by siRNA in U373 and U87 cells and found that knockdown of HMGB1 inhibited cell migration and invasion of glioma cells in vitro, which is consistent with previous report." (PMID 25772485, 2015). "The expression of HMGB1 in 15 samples of normal brain tissue and 65 samples of different-grade glioma tissue was assayed using immunohistochemistry and western blot analysis." (PMID 25574225, 2015). "We then performed RTq-PCR analysis to examine the inhibitory effect of miR-129-2 on endogenous HMGB1 expression in glioma cells." (PMID 25772485, 2015). "With the consistent expression of HMGB1, the glioma grows and progresses continually, leading to necrosis of certain lesions." (PMID 25574225, 2015). "The objective of this study was to explore the expression and the clinical and prognostic significance of high-mobility group box-1 (HMGB1) in human gliomas." (PMID 25574225, 2015). "In glioma tissues the expression of HMGB1 was higher, and the degree of expression in different pathological grade gliomas was significantly different." (PMID 25574225, 2015). "The positive rates of HMGB1 expression in normal brain and glioma tissue were 20.0% (3/15) and 76.9% (50/65), respectively." (PMID 25574225, 2015). "In the present study, immunohistochemistry and western blot analysis were used to analyze the expression rate and levels of HMGB1 in glioma tissues, and the prognostic significance of HMGB1 expression in human gliomas was examined for the first time." (PMID 25574225, 2015).
glioma (continued). "Further, functional studies demonstrated that overexpression of miR-129-2 suppressed cell growth, migration, and invasion and promoted cell apoptosis in the glioma cells, at least partially through targeting the oncogene HMGB1." (PMID 25772485, 2015). "To investigate if miR-129-2 directly targets HMGB1 in glioma cells, we amplified the wild-type HMGB1 3′UTR containing the predicted binding sites of miR-129-2, and its mutant version by the binding site mutagenesis was also constructed." (PMID 25772485, 2015). "In conclusion, HMGB1 positivity and protein expression levels are of significant clinical and prognostic value in human gliomas." (PMID 25574225, 2015). "A positive correlation was identified between HMGB1 expression levels and the pathological grades of the gliomas." (PMID 25574225, 2015). "In conclusion, our study suggests that miR-129-2 is down-regulated by DNA methylation and functions as a tumor suppressor by targeting HMGB1 in glioma cells." (PMID 25772485, 2015). "In the present study it was shown that HMGB1 has different levels of expression in normal brain and glioma tissues." (PMID 25574225, 2015). "HMGB1 is expressed in the nucleus and cytoplasm and plays an important role in the chemoresistance of glioma, in addition to acting as a broad-spectrum tumor biomarker." (PMID 25574225, 2015). "Western blot analysis showed that HMGB1 had lower levels of expression in normal brain tissue than in glioma tissue." (PMID 25574225, 2015). "To investigate the functional roles of HMGB1 in glioma cells, we knocked down HMGB1 in U373 and U87 cells by HMGB1-specific small interfering RNAs (si-HMGB1), which was confirmed by Western blot." (PMID 25772485, 2015). "HMGB1 expression was detected in the majority of patients, with 50/65 (76.9%) of gliomas being HMGB1-positive." (PMID 25574225, 2015). "In other experiments, endogenous TLR2 agonist HMGB1, released from glioma cells by targeted treatment with gancyclovir, activated DCs and facilitated therapy." (PMID 25411122, 2014). "This cytokine actually induces TLR4 expression, via hypoxia inducible factor 1-α (HIF-1α), which results in the elevation of HMGB1 in glioma cells." (PMID 25411122, 2014). "Our recent work showed that co-treatments of glioblastoma cells with the unsaturated fatty acid docosahexaenoic acid (DHA) and dPGS, as well as aminated dPG (dPGA), showed additive positive effects in killing glioma cells due to disruption of the HMGB1/RAGE axis." (PMID 41226481, 2025). "For instance, lactic acid from glioma cells stimulates TAM polarization to the M2 subtype via protein-coupled receptor 65 activation, which subsequently induces high mobility group box 1 secretion to increase glioma cell proliferation, migration, invasion, and EMT." (PMID 40722682, 2025). "In our study, we found that GPR65+TAMs could affect the secretion of HMGB1, thereby facilitating the progression and mesenchymal transition of glioma cells." (PMID 38576043, 2024). "ROS-induced paraptosis in rat T9 glioma cells was associated with the release of “danger signals” like the induction of heat shock proteins and the relocation of HMGB1 (High Mobility Group Box 1) from the nucleus to the cell periphery, thereby potentially enhancing tumor immunogenicity." (PMID 39519031, 2024). "Moreover, GPR65 was recognized as the main lactate receptor on TAMs in glioma, and its activation drives glioma progression through HMGB1 secretion via the cAMP/PKA/CREB signaling pathway." (PMID 38576043, 2024). "HMGB1 can be trafficked via EVs, including rat glioma EVs, and one may speculate that vesicles laden with alarmins and possibly pro-inflammatory cytokines could induce Inflammatory Responses in recipient astrocytes, followed by further autocrine stimulation." (PMID 39585062, 2024). "In addition, HMGB1 mRNA level showed a positive correlation with circ_0008285, whereas miR-384 expression was negatively correlated with circ_0008285 in glioma tumor specimens." (PMID 37575469, 2023).